MIR138-2 (microRNA 138-2)
Synonyms: hsa-mir-138-2; MIRN138-2; mir-138-2
Gene: MicroRNA gene on chromosome 16 (56,858,518 to 56,858,601, forward strand). Ensembl gene ENSG00000207649.
Gene Ontology:
Biological process: miRNA-mediated post-transcriptional gene silencing
Cellular component: RISC complex
Homologues: Orthologues: chimpanzee ptr-mir-138 (100% identical), macaque MIR138-2 (100% identical), dog MIR138-2 (99% identical), pig MIR138-2 (99% identical), rabbit MIR138-2 (99% identical), guinea pig MIR138-2 (85% identical), mouse Mir138-2 (85% identical). Paralogues in human: MIR138-1 (65% identical).
Diseases named in the same sentence as MIR138-2 in open-access papers:
MIR138-2 is named in the same sentence as 2 diseases in open-access papers, as found by Europe PMC text mining. Sharing a sentence is not in itself a finding about the gene and the disease. The quoted sentences say what the papers report.
cancer (1 paper, 2022). A tumor composed of atypical neoplastic, often pleomorphic cells that invade other tissues. "In addition, other genes have been involved in cancer processes, such as interference with innate immune system (SH2D3C), apoptosis (BLCAP), crossing-over regulation during meiosis (RNF212), and tumor suppression (ZDHHC14, MIR138-2, and PHTF1)." (PMID 36535927, 2022).
MIR138-2 also shares sentences with these, for which no sentence is quoted: tumor (1 paper).